GPX1 (glutathione peroxidase 1)
Diseases named in the same sentence as GPX1 in open-access papers (continued):
Sharing a sentence is not in itself a finding about the gene and the disease.
glaucoma (1 paper, 2021). Increased pressure in the eyeball due to obstruction of the outflow of aqueous humor. "We found a statistically significant association of GPX1 rs1050450 with the severity of glaucoma." (PMID 33803434, 2021). "We found no previous studies analysing the association of the GPX1 SNP with the glaucoma phenotype." (PMID 33803434, 2021). "Therefore, those with lower IOP had presumably advanced glaucoma, which might partly explain the link between GPX1 polymorphisms and lower IOP and severity of glaucoma." (PMID 33803434, 2021). "The GPX1 rs1050450 CT and TT genotypes were associated with increased risk of POAG in the Polish population, but the link with glaucoma phenotypes has not been investigated." (PMID 33803434, 2021).
glomerular disease (1 paper, 2015). "The current study, for the first time, demonstrates that the glomerular disease in a mouse model of anti-GBM-GN is associated with impaired Nrf2 activation (reduced nuclear content) along with low levels of GCLc, GCLm, and GPx1." (PMID 25785827, 2015).
Glucose intolerance (1 paper, 2025). Glucose intolerance (GI) can be defined as dysglycemia that comprises both prediabetes and diabetes. "Altogether, R. torques administration modestly alleviates glucose intolerance and increases both liver GPX1 protein levels and cecal E. coli abundance in Se-deficient mature female mice with diabetic symptoms." (PMID 41255977, 2025).
H1N1 virus infection (1 paper, 2022). "SeNPs improved the amount of glutathione peroxidase 1 in MDCK cells, which in turn prevented the apoptosis brought on by H1N1 virus infection." (PMID 36551339, 2022).
heroin addiction (1 paper, 2022). "The significant inverse association of [GPX-1] and DA agrees with the previously reported correlation between the duration of chronic heroin addiction and the gradual decrease of plasma levels of antioxidants." (PMID 36212505, 2022). "Serum GPX-1 concentration findings define the potential oxidative stress on erythrocytes in response to heroin addiction." (PMID 36212505, 2022).
HIV-1 infection (1 paper, 2022). The type species of lentivirus and the etiologic agent of acquired immunodeficiency syndrome (AIDS). "Based on the migration on SDS-PAGE and radioactive signal intensity, it was suggested that TXNRD1, GPX4 and GPX1 were downregulated in Jurkat cells after HIV-1 infection in favor of one or more low-molecular-weight selenocompounds." (PMID 35163318, 2022). "We monitored the expression of five selenoproteins, namely GPX4, GPX1, SELENOO, TXNRD1 and SELENOS, in response to HIV-1 infection at various time points and in cellular protein extracts." (PMID 35163318, 2022).
ileitis (1 paper, 2020). "In the TNF∆ARE model (TNFα over‐expression driven ileitis; B6/N background), the ilea showed a range of Paneth cell loss with the worst mice being similarly devoid of Paneth cells as Gpx1/2‐DKO mice." (PMID 32810389, 2020). "C57Bl6 (B6) mice devoid of glutathione peroxidases 1 and 2 (Gpx1/2‐DKO) develop ileitis after weaning." (PMID 32810389, 2020). "TNF∆ARE mice with low ileitis scores had microbiota compositions resembling wild‐type mice; the Splenda control Gpx1/2‐DKO mice closely resembled the non‐DKO controls." (PMID 32810389, 2020). "Here, we examine the composition of the ileitis provoking microbiota in B6 Gpx1/2‐DKO mice." (PMID 32810389, 2020). "Since pathology in B6 Gpx1/2‐DKO mice shows a dependence on NOX1, we doubt that ER stress generates the ileitis, although when pathology is underway ER stress may contribute to the Paneth cell loss." (PMID 32810389, 2020).
low grade glioma (1 paper, 2022). A grade I or grade II glioma arising from the central nervous system. "For example, GPX1 expression was a potential prognostic factor in low-grade glioma (LGG) and so was GPX8 in GBM/LGG, based on bioinformatic analysis from TCGA." (PMID 36052280, 2022).
lumbar disc degeneration (1 paper, 2025). "For example, one study showed that SeNPs rebalance redox homeostasis by activating GPx1, thereby reducing ROS levels and ameliorating lumbar disc degeneration." (PMID 41462876, 2025).
melancholia (1 paper, 2020). A subtype of depression characterized by the inability to find pleasure in positive things combined with physical agitation, insomnia, or decreased appetite. "In humans, Gpx1 activity was found to be decreased in the haemolysed erythrocytes of depressed women 32 and increased in the erythrocytes of patients with melancholia." (PMID 32281745, 2020).
memory impairment (1 paper, 2024). "Ginsenoside Re has been demonstrated to have anti-aging effects by attenuating memory impairments, involving the regulation of the angiotensin II AT1 receptor, Nrf2, GPx-1, PAFR, NFkappaB, etc.." (PMID 38966558, 2024).
multiple sclerosis (1 paper, 2025). A progressive autoimmune disorder affecting the central nervous system resulting in demyelination. "In summary, we concluded that among the two key ERS-DEGs, GPX1 has a potential causal association with multiple sclerosis (MS) and plays a protective role in MS." (PMID 40650067, 2025). "GPX1, RCN1, and UBE2D3 exhibited AUC values above 0.7 in both datasets, indicating their potential as biomarkers for multiple sclerosis." (PMID 40650067, 2025).
myopia (1 paper, 2017). "Such expression changes were evident, particularly in the late myopia dataset where a wide range of genes linked with oxidative stress were either up-regulated (GPX1, GSTA3, MT-4, APOA1, OTUB, PTGDS, HSPB1, HSPB2) or down-regulated (XHD, SLC40A1, TF, SOD3, HPGDS, BCMO1)." (PMID 28852117, 2017).
neck cancer (1 paper, 2021). "For instance, Gpx1 is responsible for preventing DNA mutation, and the disappearance of the heterozygous character of the Gpx1 gene (anti-oncogenic effect) commonly occurs in the case of breast, colon, head, or neck cancer." (PMID 34068374, 2021).
nodular sclerosis (1 paper, 2018). "In the glomeruli of patients with advanced DN, there was moderate to strong staining for Prx1, Prx2, GPx1, and catalase in the podocytes, particularly in the glomeruli having the lesions of nodular sclerosis (Kimmelstiel–Wilson lesion)." (PMID 30132841, 2018).
nuclear cataract (1 paper, 2021). A cataract (disease) that involves the lens nucleus. "GPX-1 is involved in the glutathione redox cycle and GPX-1 knockout in mice lead to the formation of age dependent nuclear cataracts and a reduced number of functional Cx46 and Cx50 channels, implying that channel oxidation lowered the gap junctional coupling conductance of MF and DF cells." (PMID 35002784, 2021).
oral squamous cell carcinomas (1 paper, 2021). "Higher GPX1 expression, on the other hand, was associated with substantial penetration of the blood vessels and low survival in hepatocellular carcinoma and oral squamous cell carcinoma." (PMID 34943522, 2021).
osteogenesis imperfecta (1 paper, 2023). Osteogenesis imperfecta (OI) comprises a heterogeneous group of genetic disorders characterized by increased bone fragility, low bone mass, and susceptibility to bone fractures with variable severity. "Therefore, targeting Gpx1 at an early phase of healing can prevent oxidative stress in hypoxic conditions and in diseases with dysfunctional TGF-B, as osteogenesis imperfecta." (PMID 36834981, 2023).
osteoporosis (1 paper, 2023). A condition of reduced bone mass, with decreased cortical thickness and a decrease in the number and size of the trabeculae of cancellous bone (but normal chemical composition), resulting in increased fracture incidence. "Additionally, decreased GPX1 enzyme activity and the development of osteoporosis have been established in postmenopausal women." (PMID 37107290, 2023).
ovarian adenocarcinoma (1 paper, 2025). An adenocarcinoma that arises from the ovary. "Treatment with CUR alone significantly inhibited the growth of human ovarian adenocarcinoma SKOV-3/CDDP CDDP-resistant subline cells by inhibition the gene expression of the antioxidant enzymes (SOD1, SOD2, GPX1, CAT, and HO1), transcription factor NFE2L2 and signaling pathway (PIK3CA/AKT1/MTOR)." (PMID 39859517, 2025).
pancreatic adenocarcinoma (1 paper, 2021). "GPX1 inhibits the EMT by regulating the Akt/GSK3β/Snail signaling axis in pancreatic adenocarcinoma (PDAC)." (PMID 35178395, 2021).
parasite (1 paper, 2023). "The expression of GPx-1 was found to be significantly increased at both 12 h and 24 h after parasite infection." (PMID 38275638, 2023).
periodontal disease (1 paper, 2023). "In a recent clinical study, it was observed that the expression of genes responsible for encoding the antioxidant enzyme products, specifically glutathione peroxidase 1 (GPX1) and thioredoxin 1 (TXN1), was significantly higher in the saliva of patients with periodontal disease." (PMID 37760090, 2023).
pneumonia (1 paper, 2025). An acute, acute and chronic, or chronic inflammation focally or diffusely affecting the lung parenchyma, caused by an infection in one or both of the lungs (by bacteria, viruses, fungi, or mycoplasma.). "In our opinion, this is the first study to identify SNPs in antioxidant (SOD1, CAT, GPX1, NOS, HMOX1, and NQO1) and immunological (IL-1α, IL1B, IL6, TNF-α, IL10, LFA-1, CR2, IL17, IL13, DEFB123, SCART1, and ICAM1) genes as potential suspects for pneumonia resistance/susceptibility in Barki ewes." (PMID 40221769, 2025). "Conversely, the expression levels of IL10, SOD1, CAT, GPX1, and NQO1 were significantly lower in the pneumonia group than in the healthy control group." (PMID 40221769, 2025).
prediabetes (1 paper, 2020). "Vitamin D supplementation modulates GPx1 levels that can favourably benefit vitamin D deficient patients with prediabetes, particularly males." (PMID 32013162, 2020). "In conclusion, vitamin D supplementation favourably enhanced GPx1 levels in adult Arabs with prediabetes, particularly in males." (PMID 32013162, 2020). "This interventional study aimed to investigate the effects of vitamin D supplementation on glutathione peroxidase 1 (GPx1) levels and other parameters in Arab adults with prediabetes." (PMID 32013162, 2020). "Hence the present study aimed to determine the effects of vitamin D supplementation on GPx1 levels in Saudi adults with prediabetes." (PMID 32013162, 2020). "We hypothesize that improving vitamin D status may favourably regulate GPx1 activity and may, therefore, delay the progression of individuals with prediabetes to T2DM." (PMID 32013162, 2020). "Our findings showed a significant positive correlation between GPx1 levels with 25(OH)D levels, and may, therefore, reduce oxidative stress in patients with prediabetes." (PMID 32013162, 2020).
prion disease (1 paper, 2011). A transmissible disease that is caused by a protein that is able to induce abnormal folding of normal cellular proteins, leading to characteristic spongiform brain changes, which are associated with neuronal loss without an inflammatory response. "Further analysis, including immunohistochemical determination of GPx-1 in scrapie brains or in vitro studies, would be necessary to elucidate a possible neuroprotective role of this enzyme in prion diseases." (PMID 21629698, 2011).
prostate tumor (1 paper, 2018). "Nuclear localization of GPX1 was also observed in both primary prostate epithelial cells and the immortalized prostate-derived cell line RWPE-1, but not in LNCaP or PC3 prostate tumor-derived cell lines." (PMID 30453672, 2018).
pulmonary fibrosis (1 paper, 2017). Chronic progressive interstitial lung disorder characterized by the replacement of the lung tissue by connective tissue, leading to progressive dyspnea, respiratory failure, or right heart failure. "In addition, present study showed that the mRNA and protein expression levels of Nrf2, Ho-1, and Gpx1 in mouse pulmonary fibrosis induced by BLM were significantly increased, but in Bach1 were significantly decreased with PFD treatment for 4 weeks." (PMID 28420366, 2017). "Furthermore, it was also found that the activity and expression of Gpx1 and Ho-1 were significantly decreased in damaged lung of a mouse with bleomycin-induced pulmonary fibrosis, suggesting that the decline of Nrf2 dependent antioxidants promoted the formation of fibrosis." (PMID 28420366, 2017).
pulmonary TB (1 paper, 2020). "We also found increased plasma expression of glutathione synthetase (GSS) in pulmonary TB and glutathione Peroxidase-1 (GPX1) in patients with COPD." (PMID 33023021, 2020).
pyometra (1 paper, 2024). "The elevation of GPX1 in the uterus of cats with pyometra may represent a tissue response to oxidative stress aimed at restoring redox homeostasis." (PMID 39457917, 2024). "Unlike what was observed in dogs, cats with pyometra exhibit increased protein and gene expression of GPX1 in the uterus, as well as increased plasma GPX levels." (PMID 39457917, 2024).
renal carcinoma (1 paper, 2019). A carcinoma arising from the epithelium of the renal parenchyma or the renal pelvis. "Colony formation assays reveal that knockdown of GPX1 can reduce clonogenic capacity of renal cancer cells." (PMID 31844035, 2019). "Considering the high expression level of GPX1 in detecting renal cancer cell lines, we used the sh-RNA knockdown method." (PMID 31844035, 2019). "In terms of function, GPX1 promotes proliferation, colony formation capacity, migration and invasion of renal cancer cells." (PMID 31844035, 2019). "To explore the function of GPX1 in renal cancer, we first examined the effect of GPX1 on the growth of renal cancer cells in vitro, a key factor in tumor volume enlargement." (PMID 31844035, 2019). "CCK8 assays show that knockdown of GPX1 can inhibit the proliferation of renal cancer cells." (PMID 31844035, 2019). "To investigate whether GPX1 affects the migration and invasion of renal cancer cells, we performed the transwell assays." (PMID 31844035, 2019).
retinal degeneration (1 paper, 2021). Degeneration of the retina. "VEGF-B protects retinal cells against oxidative stress and rescues retinal degeneration by upregulating the antioxidative genes GPX1 and SOD1." (PMID 34631708, 2021).
sarcopenia (1 paper, 2020). Progressive decline in muscle mass due to aging which results in decreased functional capacity of muscles. "Further analysis of pathways activated by Gpx1 and Gsta4 warrant attention because dissection of the involved mechanisms could lead to new therapies for sarcopenia." (PMID 33067900, 2020). "Increased capacity for enzymatic scavenging of superoxide radical could be a major protective adaptation against free radical damage in muscle and may therefore be a major protection against the development or onset of sarcopenia, and Gpx1 and Gsta4 might additionally be involved." (PMID 33067900, 2020).
scrapie (1 paper, 2011). A fatal disease of the nervous system in sheep and goats, characterized by pruritus, debility, and locomotor incoordination. "In accordance with that finding, we observed a positive association between the expression of this gene and prion deposition and a significant overexpression of GPx-1 in scrapie medullae (FC: 2.03)." (PMID 21629698, 2011).
trichinellosis (1 paper, 2024). "Our hypothesis was to demonstrate the possible pathogenic role of miltefosine in the treatment of trichinellosis through three different pathways (inflammation (GATA 3), apoptotic (caspase-3), and oxidant/antioxidant pathways (GPX1))." (PMID 38489009, 2024).
triple-negative breast carcinoma (1 paper, 2021). An invasive breast carcinoma which is negative for expression of estrogen receptor (ER), progesterone receptor (PR), and human epidermal growth factor receptor 2 (HER2). "Recently, we reported a role for GPx1 in the migratory activity of triple-negative breast cancer (TNBC) cells, including MDA-MB-231 cells." (PMID 34158609, 2021).
viral myocarditis (1 paper, 2021). Myocarditis that is caused by an infection with a viral agent. "Studies in adult rodents demonstrate that GPx1 deficiency exacerbates injury induced by ischemia/reperfusion, diquat and paraquat exposure, and viral myocarditis." (PMID 33672905, 2021).
vitamin D deficiency (1 paper, 2015). A nutritional condition produced by a deficiency of VITAMIN D in the diet, insufficient production of vitamin D in the skin, inadequate absorption of vitamin D from the diet, or abnormal conversion of vitamin D to its bioactive metabolites. "Vitamin D deficiency increased IL-6 levels by 22% compared to AI females, thereby elevating GPx1 protein content by 29%." (PMID 26020962, 2015). "In vitamin D deficiency however, excessive inflammation, as reflected by high IL-6 levels, increases GPx1 activity as a means of reducing oxidative protein injury." (PMID 26020962, 2015).
Zinc deficiency (1 paper, 2013). A deficiency of the essential metal Zinc; an essential cofactor for many enzymes. "The protein levels of iNOS, SOD-2 (Mn-SOD), GPx1/2 and TrxR1 were not affected by either ethanol consumption or dietary zinc deficiency." (PMID 24155903, 2013).